CXCL1 (C-X-C motif chemokine ligand 1)
Diseases named in the same sentence as CXCL1 in open-access papers (continued):
Sharing a sentence is not in itself a finding about the gene and the disease.
pustular psoriasis (1 paper, 2024). "Furthermore, skin explants of pustular psoriasis cultured with a neutralizing anti-IL-26 mAb but not anti-IL-17A mAb completely inhibited the expression of CXCL1, CXCL8, and IL1A, confirming the specific role of IL-26 as a driver of pathogenic autoinflammation circuits." (PMID 38448036, 2024).
renal carcinoma (1 paper, 2013). A carcinoma arising from the epithelium of the renal parenchyma or the renal pelvis. "CXCL1 has been reported to be overexpressed in gastric, colon, skin and renal cancers." (PMID 23815949, 2013).
renal sclerosis (1 paper, 2025). "Consistent with improved blood BUN levels, Nutlin 3b relieved hyalination, a sign of renal sclerosis, SASP (Tnfα, Cxcl1, Ccl5) and the senescent marker p16Ink4a in aged kidneys." (PMID 41392167, 2025).
Respiratory tract infection (1 paper, 2010). An infection of the upper or lower respiratory tract. "In mice infected with S. pyogenes, there was an inverse relationship between bacterial load and CXCL1/KC levels during respiratory tract infection." (PMID 20158613, 2010).
ROSAH syndrome (1 paper, 2022). "Consistent with the observations in patients with ROSAH syndrome, knock-in mice with the Alpk1 T237M mutation had elevated serum levels of CXCL1, CXCL10 and CCL2." (PMID 35868845, 2022). "Patients with ROSAH syndrome also demonstrated elevations of additional cytokines and chemokines including plasma CXCL10 (interferon gamma-induced protein 10 (IP-10)) and serum CXCL1 (GRO-alpha (previously known as neutrophil-activating protein 3))." (PMID 35868845, 2022).
RSV bronchiolitis (1 paper, 2019). "Upregulations in cytokines and chemokines responsible for neutrophil recruitment and/or activation (i.e., elastase, CXCL1, G-CSF, and GM-CSF) have been linked to heightened airway inflammation and RSV bronchiolitis." (PMID 31398832, 2019).
scrapie (1 paper, 2016). A fatal disease of the nervous system in sheep and goats, characterized by pruritus, debility, and locomotor incoordination. "Cxcl11 and Cxcl1 were the only genes upregulated by BE and not by scrapie in these samples." (PMID 27046083, 2016).
secretory otitis media (1 paper, 2024). "It has recently been shown, in secretory otitis media (SOM), that different inflammatory mediators, such as CXCL1, IL-16, IL-8, IL-17, IL-1β, CXCL10, and CXCL9, were found in high concentrations in middle ear fluids, in association with the presence of bacterial and viral nucleic acid levels." (PMID 38541021, 2024).
severe acute respiratory syndrome (1 paper, 2024). A viral respiratory infection caused by the SARS coronavirus. "Interestingly, the deletion of the caspase-11 gene has been proved to be associated with reduced secretion of CXCL1 in severe acute respiratory syndrome (SARS)." (PMID 38459541, 2024).
shigellosis (1 paper, 2023). Shigellosis is a bacterial infection leading to dysentery and is caused by Shigella, which are small, ubiquitous Gram-negative bacteria belonging to the enterobacteria family. "CXCL1 and IL-1β are NF-κB-induced cytokines previously implicated in driving disease during shigellosis by initiating inflammation and promoting innate immune cell recruitment to the gut." (PMID 36645406, 2023).
skin squamous cell carcinoma (1 paper, 2022). A carcinoma arising from the squamous cells of the epidermis. "In skin squamous cell carcinomas, upregulation of ETV1 was sufficient to induce most CAF effectors upregulated by fibroblast growth factor (FGF), which could promote the secretion of multiple chemokines with macrophage-recruiting activity including CXCL1, CXCL10, and CXCL11." (PMID 35860243, 2022).
skin toxicity (1 paper, 2021). "Interestingly, increased levels of CXCL1 have been reported in the blood of UVB-irradiated mice, and inhibition of CXCL1 was sufficient to improve UVB-induced skin toxicity." (PMID 33804336, 2021).
spondylolisthesis (1 paper, 2026). A condition in which there is forward displacement of a vertebral bone over the on below it. "IP MR identified risk-increasing associations for LSS (4E-BP1 and interleukin-4), spondylolisthesis (CXCL1, CXCL5, FGF-5, IL-15RA, and IL-4) and IDD (IL-20RA and IL-6), while IL-18 showed a protective association with IDD that remained robust after multiple-testing correction." (PMID 42317351, 2026).
streptococcal infection (1 paper, 2013). Any of the several infectious disorders caused by members of streptococcus, a genus of gram positive bacteria belonging to the family Streptococcaceae. "A functional role of CXC chemokines has been proposed in streptococcal infections and we have demonstrated that M1 protein is a potent stimulator of CXCL1 and CXCL2 production in the lung." (PMID 23951087, 2013). "Notably, administration of NSC23766 completely inhibited M1 protein-induced gene expression of CXCL1 and CXCL2 in alveolar macrophages, indicating that Rac1 activity mediates macrophage production of CXC chemokines in streptococcal infections." (PMID 23951087, 2013).
tauopathy (1 paper, 2026). Neurodegenerative disorders involving deposition of abnormal tau protein isoforms (tau proteins) in neurons and glial cells in the brain. "Concordantly, CST reduced expression of CD68, GFAP, IL-6, TNF-α, CXCL1, and CXCL10, extending its known peripheral anti-inflammatory actions 20,38 to the central nervous system and establishing CST as a regulator of neuroimmune homeostasis in Tauopathy." (PMID 41509358, 2026).
trachoma (1 paper, 2023). "While there were too few participants with active trachoma (clinical grades F > 1, P > 2, n = 2) to detect changes in active disease, IL-10, IL-8 and CXCL1 were significantly increased in those with clinical grades F > 0 or P > 0 (p = 0.0031, 0.014, 0.037 respectively, logistic regression)." (PMID 37862368, 2023).
trichomoniasis (1 paper, 2025). An infection that is caused by Trichomonas. "As trichomoniasis has been linked to an increased risk of UCC, we purpose that TV-EV-induced CXCL1 secretion may contribute to the progression of UCC, which requires further investigation." (PMID 40455858, 2025).
unstable angina (1 paper, 2024). "Previous studies have shown that higher CXCL1 expression is present in patients with unstable angina, enhances the secretion of MMPs46, and activates macrophages in atherosclerotic lesions." (PMID 38806571, 2024).
uterine corpus endometrial carcinoma (1 paper, 2023). A endometrial carcinoma (disease) that involves the body of uterus. "Additionally, according to the GEPIA portal, which compares data from the Cancer Genome Atlas (TCGA) with data from normal tissues from GTEx, CXCL1 expression is upregulated in uterine corpus endometrial carcinoma." (PMID 37108425, 2023). "According to the GEPIA portal, the expressions of CXCL1 do not affect the prognosis for patients with uterine corpus endometrial carcinoma." (PMID 37108425, 2023).
uveal melanoma (1 paper, 2007). A melanoma derived from melanocytes of the uveal tract. "All 5 human uveal melanoma cell line cytospins stained positive for CXCL1, CXCL8, and their receptors CXCR2 and CXCR1 respectively." (PMID 17261188, 2007). "The migratory ability of the 5 human uveal melanoma cell lines was positively influenced by the four chemotactic factors tested, namely CXCL12, CXCL8, CXCL1, and HGF." (PMID 17261188, 2007). "The aim of this study was to characterize the presence and roles of CXCL12, CXCL8, CXCL1, and HGF in five human uveal melanoma cell lines, using different methods, in order to ascertain their significance in this disease." (PMID 17261188, 2007). "In conclusion, characterizing the expression of CXCL12, CXCL8, CXCL1, and HGF in uveal melanoma cell lines leads us to a better understanding of how these cytokines are integral in the metastatic process." (PMID 17261188, 2007). "Migratory stimulation of uveal melanoma cell lines (SOM196B, SOM157d, SOM267, SOM269) with CXCL1 has been previously shown." (PMID 17261188, 2007). "All 5 human uveal melanoma cell lines were shown to produce significant levels of CXCL8, CXCL1, and HGF." (PMID 17261188, 2007). "Demonstration of a functional role for CXCL12, CXCL8, CXCL1, and HGF in uveal melanoma may yield novel therapeutic targets." (PMID 17261188, 2007). "The present study was designed in order to analyze the expression of CXCL12, CXCL8, CXCL1, and HGF in five human uveal melanoma cell lines (92.1, SP6.5, MKT-BR, OCM-1, UW-1) and to investigate the effects of these factors on the migratory ability of the 5 cell lines." (PMID 17261188, 2007). "All 5 human uveal melanoma cell lines (92.1, SP6.5, MKT-BR, OCM-1, UW-1) migrated towards the selected chemo-attractants at a level greater than the selected negative control (serum-free RPMI media) (p < 0.05) except for cell line OCM-1 towards chemokine CXCL1 (p-value = 0.0575)." (PMID 17261188, 2007).
uveitis (1 paper, 2022). An inflammatory process affecting a part of or the entire uvea. "Third, given several differences of cytokine/chemokine transcript regulation (e.g. of Cxcl1 and Cxcl10) using RT-qPCR, it would be of interest to confirm these findings at the protein level, as well as future mechanistic studies to explore Nlrp12-mediated protection against uveitis." (PMID 35313917, 2022).
vascular tumor (1 paper, 2024). "IHC scores of CXCL1、CXCL2、IL6、ABCC1、LRP、BCL2, vascular tumor thrombus, ascites cancer cells, maximum tumor diameter, neoadjuvant chemotherapy, and HE4 were included in the prediction model." (PMID 38509620, 2024).
viral meningitis (1 paper, 2021). Inflammation of the membranes surrounding the brain and spinal cord due to a viral infection. "Like CXCL1, CXCL6 serves as a neutrophil chemoattractant and is elevated in bacterial and viral meningitis." (PMID 34863228, 2021).
vitamin D deficiency (1 paper, 2014). A nutritional condition produced by a deficiency of VITAMIN D in the diet, insufficient production of vitamin D in the skin, inadequate absorption of vitamin D from the diet, or abnormal conversion of vitamin D to its bioactive metabolites. "Vitamin D deficiency significantly enhanced the basal expression of IL-1β, IL-6, and TNF-α in the lungs of mice, while did not influence the basal expression of CXCL1 and CCL3." (PMID 24926881, 2014).
xeroderma pigmentosum (1 paper, 2022). Xeroderma pigmentosum (XP) is a rare genodermatosis characterized by extreme sensitivity to ultraviolet (UV)-induced changes in the skin and eyes, and multiple skin cancers. "During skin exposure to UV light, xeroderma pigmentosum group A (XPA) protein-deficient mice show an increase in CXCL1/KC expression, a paralog for human CXCL1." (PMID 36613652, 2022).
tumor (1,261 papers, 2006 to 2026). "It was found that secretion of CXCL1 by CAFs also reactivated dormant OSCC cells by down-regulating DEC2 expression in tumor cells, and this process was significantly associated with the recurrence and infiltration of cancer-associated fibroblasts." (PMID 41445742, 2025). "Inflammatory cancer-associated fibroblasts (iCAFs) are a pro-inflammatory subset of tumor-associated fibroblasts characterized by high secretion of cytokines and chemokines, most notably CXCL1." (PMID 40940809, 2025). "Nos2 has been demonstrated to promote NO synthesis, tumor death, and increasing pathogenic microorganisms, secreting a large number of pro-inflammatory factors, including IL-1β, C-X-C motif chemokine ligand 1 (CXCL1), and others." (PMID 40002899, 2025). "Recent findings suggest that visfatin can drive the differentiation of monocytes into M2-like tumour-associated lymphocytes by inducing CXCL1, with M2-like macrophages playing a crucial role in escalating tumour malignancy rates." (PMID 40414892, 2025). "The most common chemokine secreted by tumor-associated macrophages, CXCL1, is found on chromosome 4." (PMID 40584290, 2025). "In breast cancer, CSCs secrete autocrine chemokine CXCL1, which activates pathways associated with immune evasion and tumor promotion by modulating the factors regulating tumor growth and immunosuppression." (PMID 40647402, 2025). "Elevated CXCL1 expression has also been linked to improved tumor control through the recruitment and activation of neutrophils." (PMID 40108668, 2025). "CXCL1, a chemokine known for its role in inflammation and wound healing, has been implicated in tumor progression and the modulation of the TME." (PMID 40490643, 2025). "IL-17 directly induces IL-6, G-CSF, and CXCL1 production, attracting tumor-associated neutrophils and rendering them the dominant immune cell population within the tumor." (PMID 41516132, 2025). "On the other hand, it should be mentioned that CXCL1 causes the recruitment of G-MDSCs into the tumor niche —cells that inhibit the action of anti-tumor lymphocytes and thus reduce the effectiveness of immunotherapy." (PMID 40427171, 2025). "The chemokine CXCL1, which is expressed in tumor-associated fibroblasts, is associated with poor prognosis." (PMID 39456897, 2024). "Tumor-associated dendritic cells (TADCs) secreted CXCL1, which in turn increased the expression of the CSC markers CD44 and CD133 on the SW620 CRC cell line and promoted their stemness." (PMID 38254219, 2024). "In the context of cancer, CXCL1 has been implicated in various aspects of tumor progression and metastasis, making it a potential target for anticancer therapies." (PMID 39057432, 2024). "Brain metastatic variant tumor cells expressed CXCL1 and CXCL8 in a c-Met signaling-dependent manner." (PMID 38786066, 2024). "The elevated squalene inhibits CXCL1 transcription through its impact on the NF-κB pathway via p65, and thus reduces the recruitment of myeloid-derived suppressor cells (MDSCs) and tumor-associated macrophages (TAMs) into the tumor microenvironment." (PMID 39763673, 2024). "The CXCL-1 expression in the cytoplasm was associated with the tumor status, nodal spread, and distant metastasis." (PMID 38540782, 2024). "The chemokine CXCL1, vital in inflammatory diseases and tumors, shows that its increased presence in BC stroma is associated with higher tumor grade, disease recurrence, and lower patient survival." (PMID 39020010, 2024). "The tumor necrosis factor (TNF) produced by neutrophils triggers an excessive production of C-X-C motif chemokine ligand 1 (CXCL1) in both tumor cells and cancer-associated fibroblasts (CAFs), resulting in the suppression of T cells." (PMID 39001498, 2024).
tumor (continued). "CXCL1, a chemokine that recruits neutrophils to the tumor site, is associated with tumor progression and metastasis." (PMID 39456897, 2024). "Collectively, EV‐Apo/CXCL1 signalling appears to play a crucial role in multiple tumour‐associated biological processes, thereby acting its potential as a valuable therapeutic target for cancer treatment." (PMID 39051750, 2024). "For instance, CXCL1 promoted SC cell migration and SC xenograft growth, and CXCL1 expression showed a positive association with the inferior prognosis and tumor metastasis in SC." (PMID 39007996, 2024). "CXCL1 recruits macrophages into the TME, where they are remodelled into tumour-associated macrophages and further increase the inflammation level and CXCL1 expression." (PMID 37037815, 2023). "Mechanistically, intratumoral P. gingivalis recruited tumor-associated neutrophils by increasing the secretion of neutrophilic chemokines (C-X-C motif chemokine ligand 1 (CXCL1), CXCL2, C-X-C motif chemokine receptor 2 (CXCR2), IL-17F, S100a8 and S100a9)." (PMID 37868956, 2023). "In a mouse model of breast cancer, tumor-associated mesenchymal stromal cells released CXCL1, CXCL2 and CXCL5, leading to increased neutrophil recruitment at primary tumor sites." (PMID 37566060, 2023). "For this reason, CXCL1 is associated with so-called “tumor budding” —the appearance of either single cancer cells or small clusters of cancer cells at the invasive front of tumors." (PMID 37408240, 2023). "The experiments demonstrated that transmembrane TNF-TNFR2 signaling upregulated the expression of Cxcl1 in tumor cells and cancer-associated fibroblasts (CAFs), leading to increased pro-inflammatory signaling." (PMID 37455286, 2023). "CXCL1 causes the recruitment of G-MDSCs, bone marrow-derived mesenchymal cells, and neutrophils to the tumor niche." (PMID 37408240, 2023). "A study demonstrated that adiponectin, a specific adipocytokine with oncogenic effects, caused tumor cells to secrete CXCL1 to induce stromal cell senescence." (PMID 37046588, 2023). "CXCL1 also causes the recruitment of granulocytic-myeloid-derived suppressor cells (G-MDSCs) to the tumor niche in ESCC tumors." (PMID 37408240, 2023). "CXCR1/CXCR2 ligands, including CXCL1-3, 5–8 are produced by endothelial cells, tumor-associated macrophages, cancer-associated fibroblasts, adipocytes, and cancer cells." (PMID 37270599, 2023). "Some show that a higher CXCL1 expression in the tumor is associated with a worse prognosis for the patient." (PMID 37408240, 2023). "For example, CXCL1 secreted by tumor-associated dendritic cells (TADCs) increases the CSCs of colon cancer by promoting CD133 expression and acetaldehyde dehydrogenase activity." (PMID 37124519, 2023). "This action of CXCL1 should be understood as part of a broader meshwork of tumor-associated mechanisms." (PMID 37408240, 2023). "Intriguingly, multiple studies have demonstrated that CXCL1 is closely associated with tumor radiosensitivity." (PMID 37468464, 2023). "CCL3 and CXCL1 are pro-inflammatory cytokines and recruit tumor-killing cells, while S100A8/A9 is linked to metastasis." (PMID 37553342, 2023). "Due to the hypoxic conditions in tumor, tumor cells express more neutrophil-associated chemokines (CXCL1, CXCL2, and CXCL5) and HMGB1 to rapidly recruit neutrophils." (PMID 38023616, 2023). "The presence of tumor derived CXCL1 was linked to the upregulating of immunosuppressive granulocytic MDSCs into the tumor." (PMID 37497236, 2023). "Tumor-associated fibroblasts, an important component of the tumor environment, have been found to cause malignant transformation of normal fibroblasts and inhibit reactive oxygen species through the secretion of CXCL1." (PMID 37468464, 2023).